MIR107 (microRNA 107)
Synonyms: hsa-mir-107; MIRN107; miR-107
Gene: MicroRNA gene on chromosome 10 (89,592,747 to 89,592,827, reverse strand). Ensembl gene ENSG00000198997.
Gene Ontology:
Biological process: miRNA-mediated post-transcriptional gene silencing
Cellular component: RISC complex
Homologues: Orthologues: chimpanzee ptr-mir-107 (100% identical), macaque mml-mir-107 (100% identical), pig ssc-mir-107 (100% identical), rabbit MIR107 (100% identical), guinea pig MIR107 (98% identical), zebrafish dre-mir-107 (89% identical), tropical clawed frog xtr-mir-103-1 (79% identical), zebrafish dre-mir-103 (77% identical), zebrafish mir107b (77% identical). Paralogues in human: MIR103A2 (83% identical), MIR103A1 (78% identical).
Diseases named in the same sentence as MIR107 in open-access papers:
MIR107 is named in the same sentence as 3 diseases in open-access papers, as found by Europe PMC text mining. Sharing a sentence is not in itself a finding about the gene and the disease. The quoted sentences say what the papers report.
autoimmune lymphoproliferative syndrome (1 paper, 2011). Autoimmune lymphoproliferative syndrome (ALPS) is a rare, inherited disorder characterized by non-malignant lymphoproliferation, multilineage cytopenias, and a lifelong increased risk of Hodgkin's and non-Hodgkin's lymphoma. "MIR107 plays a role in inhibiting differentiation in granulocytic, monocytic, and B-lymphoid lines, whereas FAS is involved with apoptosis, and mutations in FAS are known to cause autoimmune lymphoproliferative syndrome." (PMID 22087757, 2011).
prostate carcinoma (1 paper, 2021). A carcinoma that arises from epithelial cells of the prostate gland. "Moreover, human MIR107 has been reported to exert pleiotropic functions in human bladder and prostate cancer." (PMID 34573432, 2021). "Independently, Mir107 has been shown to be expressed at E12.5 in the embryonic mouse metanephros and was found to exert pleiotropic functions in the human bladder and prostate cancer." (PMID 34573432, 2021).
tumor (1 paper, 2017). "Among these miRNAs, Mir107 and Mir361 have been reported to suppress tumor growth and stem cell growth." (PMID 28725177, 2017).